GPX3 (glutathione peroxidase 3)
Diseases named in the same sentence as GPX3 in open-access papers (continued):
Sharing a sentence is not in itself a finding about the gene and the disease.
kidney damage (3 papers, 2013 to 2024). "A decrease in GPX3 mRNA expression was observed at 26 weeks of age, an age younger than at which changes can be seen in kidney biopsy, which suggests that GPX3 is a potential early marker of kidney damage." (PMID 23519111, 2013). "Indeed, some studies highlighted the modulation of GPx3 in the course of kidney damage in different species." (PMID 34679050, 2021). "Since decreased GPX3 mRNA expression was observed at 26 weeks, which is younger than the age when pathological changes can be seen in kidney biopsies, GPX3 may serve as an early marker for kidney damage." (PMID 23519111, 2013). "GPX3 reflects fat accumulation and might serve as an early marker for kidney damage." (PMID 39590877, 2024).
liver cancer (3 papers, 2014 to 2025). An epithelial or non-epithelial malignant neoplasm that arises from the liver. "Secondly, we explored the tumor suppressive activity of GPx3 in vitro by administration of rGPx3 or forced expression of GPx3 in different liver cancer cell lines." (PMID 25333265, 2014). "Thirdly, we demonstrated the anti-tumor effect of GPx3 in vivo using ectopic and orthotopic liver cancer models." (PMID 25333265, 2014). "Most importantly, we further demonstrated therapeutic value of GPx3 using hiPSC-MSCs as a delivery vehicle in liver cancer models." (PMID 25333265, 2014). "GPx3 inhibits tumor invasion by inhibiting the JNK-Cjun-MMP2 pathway in liver cancer." (PMID 34926458, 2021). "It implied that other underlying mechanism might be existed for tumor suppressive activity of GPx3 in liver cancer." (PMID 25333265, 2014). "The same trend could also be observed in orthotopic liver cancer model that activation of NFκB was inhibited by the over-expression of GPx3 through deactivation of Erk." (PMID 25333265, 2014).
lung adenocarcinoma (3 papers, 2020 to 2024). A carcinoma that arises from the lung and is characterized by the presence of malignant glandular epithelial cells. "For example, data from the Cancer Genome Atlas (TCGA) demonstrate that low expression of GPx3 is associated with poor survival in lung adenocarcinoma and low-grade glioma." (PMID 32781581, 2020). "Examining available TCGA methylation data sets also demonstrates that GPx3 expression levels negatively correlate with increased GPX3 gene methylation in tumor specimens such as lung adenocarcinoma." (PMID 32781581, 2020). "It is hypothesized that LDHA, GPX3 and DOCK4 are new potential targets for lung adenocarcinoma, which can achieve breakthroughs in prognosis prediction, targeted prevention and treatment of lung adenocarcinoma and provide important guidance for anti-tumor." (PMID 38213730, 2024).
myelodysplastic syndrome (3 papers, 2013 to 2020). A clonal hematopoietic disorder characterized by dysplasia and ineffective hematopoiesis in one or more of the hematopoietic cell lines. "Four of these polymorphisms were located in oxidative damage/DNA repair genes (LIG1, RAD52, MSH3 and GPX3), which may play important roles in the pathobiology of myelodysplastic syndromes." (PMID 23339595, 2013). "GPX3 methylation was increased in patients with myelodysplastic syndrome (MDS) progressing or transforming to secondary AML (sAML)." (PMID 33369453, 2020).
pancreatic cancer (3 papers, 2022 to 2025). "GPX3 suppresses the proliferation, migration, and invasion of pancreatic cancer cells by modulating the JNK/c-Jun signaling pathway and enhances their sensitivity to chemotherapy." (PMID 40092686, 2025).
stomach cancer (3 papers, 2021 to 2025). "In stomach tumors, we found a statistically significant reduction in the amount of GPX3 DNA copies (P < 0.001)." (PMID 35069731, 2022).
systemic inflammatory response syndrome (3 papers, 2011 to 2021). SIRS is a serious condition related to systemic inflammation, organ dysfunction, and organ failure. "For example, in a study on critically ill patients in an intensive care setting, decreased GPX3 levels were associated with a systemic inflammatory response syndrome (SIRS)." (PMID 22017790, 2011). "Decreased GPx3 activity has been observed in patients with systemic inflammatory response syndrome and possessed a predictive value for this syndrome." (PMID 32862561, 2020). "According to Manzanares’ finding (2008), patients with systemic inflammatory response syndrome (SIRS) showed significant decrease in the expression of GPX3." (PMID 33926569, 2021).
acute myeloid leukemia (2 papers, 2017 to 2020). Acute myeloid leukemia (AML) is a group of neoplasms arising from precursor cells committed to the myeloid cell-line differentiation. "The impact of low expression of Glutathione peroxidase 3 (GPX3) on the clinical course of acute myeloid leukemia (AML) is poorly investigated." (PMID 33369453, 2020). "GPX3 methylation density was significantly increased during the progression from MDS to secondary acute myeloid leukemia (sAML) in three follow‐up paired patients." (PMID 27891827, 2017). "GPX3 methylation was identified in 15% (17/110) MDS patients, and significantly higher than controls, and lower than acute myeloid leukemia (AML) patients (P = 0.024 and 0.041)." (PMID 27891827, 2017).
adenoma (2 papers, 2018 to 2025). A neoplasm arising from the epithelium. "GPX2 and TXNRD3 showed a higher expression and GPX3, SELENOP, SELENOS, and SEPHS2 exhibited a lower expression in the disease tissue from adenomas and both cancer groups (p-values from 0.023 to <0.001)." (PMID 30469315, 2018). "These included increasing down-regulation of GPX3, SELENOP, SELENOS, and SEPHS2 and up-regulation of GPX2, SELENOH, and TXNRD3, in groups of normal-matched tissues, adenomas, and adenomas with HGD." (PMID 30469315, 2018).
autoimmune thyroid disease (2 papers, 2021 to 2023). Inflammatory disease of the thyroid gland due to autoimmune responses leading to lymphocytic infiltration of the gland. "During the in situ hybridization of tissue from a gland affected by autoimmune thyroiditis (M. Hashimoto), the very strong expression of GPx3 was seen in residual follicular structures whose infiltrating lymphocytes and fibrous structure were devoid of any GPx3 signal." (PMID 36834802, 2023).
Balkan endemic nephropathy (2 papers, 2023 to 2024). "Therefore, patients with Balkan endemic nephropathy (BEN) carrying a variant GPX3 genotype should be more frequently monitored for the possible development of upper-tract urothelial carcinoma." (PMID 39125992, 2024).
benign prostatic hyperplasia (2 papers, 2021 to 2025). A non-cancerous nodular enlargement of the prostate gland. "In addition, Loss of glutathione peroxidase 3 encoded by Gpx3 induces ROS and contributes to prostatic hyperplasia." (PMID 34803695, 2021). "In the hyperplasia model, GPX3 inhibits AMPK and upregulates Nrf2 in the prostate cells to improve benign prostatic hyperplasia." (PMID 40529489, 2025).
cataract (2 papers, 2014 to 2020). Partial or complete opacity of the crystalline lens of one or both eyes that decreases visual acuity and eventually results in blindness. "GPX3 can downregulate cataracts formation by upregulating glutathione peroxidase 3, which decreases the oxidative stress in the anterior capsular epithelial cells." (PMID 33213085, 2020). "The up-regulation of GPX3 is of particular interest, since it was shown previously that cataracts contain elevated levels of oxidants such as dehydroascorbic acid (DHA), indicative of oxidative stress, linked to a potentially elevated level of extracellular glutathione peroxidase GPX3." (PMID 24828575, 2014).
clear cell ovarian adenocarcinoma (2 papers, 2010 to 2020). "While the mechanism behind overexpression of GPx3 in patients with clear cell ovarian adenocarcinoma is unclear, GPx3 was shown to contribute to platinum and taxane-based chemoresistance." (PMID 32781581, 2020).
coronary atherosclerosis (2 papers, 2019 to 2025). Atherosclerosis of the coronary vasculature. "Gene polymorphisms in superoxide dismutase (SOD2 and SOD3), glutathione peroxidase-3 (GPX3), and glutathione S-transferase theta-1 (GSTT1) may enable oxidative stress-related lipid abnormalities and severity of coronary atherosclerosis." (PMID 31396447, 2019).
endometrial tumor (2 papers, 2010 to 2014). "The production of hydrogen peroxide in the endometrial tumors displaying loss of Gpx3 expression as well as in the endometrial samples with normal/high expression was measured." (PMID 21106063, 2010). "The expression of Met in the rat tumors was slightly higher in the endometrial tumors with a loss of Gpx3 expression." (PMID 21106063, 2010). "It was also revealed that Gpx3 displayed the most significantly altered gene expression in comparisons among endometrial tumors and normal/pre-malignant endometrium." (PMID 21106063, 2010). "Preliminary results also suggest that the production of H2O2 is higher in rat endometrial tumors with down-regulated Gpx3 expression." (PMID 21106063, 2010). "In this study, we sought to confirm the previously demonstrated down-regulation of Gpx3 expression from the microarray study, of a selection of previously used rat endometrial tumors." (PMID 21106063, 2010). "Paradoxically, downregulation of GPX3 in absence of promoter hypermethylation is associated with GPX3 gene deletion in endometrial tumor cell line (NUT84)." (PMID 24790704, 2014). "The production of hydrogen peroxide in one rat endometrial tumor cell line (NUT12) with loss of expression of Gpx3 and in two non-malignant endometrial cell lines (NUT43 and NUT56) with Gpx3 expression was measured." (PMID 21106063, 2010). "The decreased mRNA expression of Gpx3 in rat endometrial tumors might result in an impaired defense against endogenous and exogenous genotoxic compounds, which could potentially lead to an increased mutation rate including genes involved in carcinogenesis." (PMID 21106063, 2010). "We could not confirm any such tumor suppressor activity of GPX3/Gpx3 either in human or rat endometrial tumors." (PMID 21106063, 2010).
Hypoglycemia (2 papers, 2011 to 2016). A decreased concentration of glucose in the blood. "We have previously shown by qPCR, the increase of Gpx3 (the top gene up-regulated by hypoglycemia; fold change = 4.8), and Gsto-1 (up-regulated by hypoglycemia; fold change = 1.9) in comparison with euglycemic control situation." (PMID 26918849, 2016). "Analysis of retinal explants showed that in vitro exposure to low glucose (2 mM) for a 48-h period significantly increased the expression of Gpx3 and Gsto1 to the same extent as in vivo hypoglycemia." (PMID 21738719, 2011). "In mouse, hypoglycemia induced up-regulation of Gpx3 and Gsto1, which may partially explain the 40% decrease of retinal GSH scavenger seen in our experiments." (PMID 21738719, 2011). "We also observed that both Gpx3 and Gsto1 enzymes, which were up-regulated during a single hypoglycemic clamp, were indeed down-regulated (Gpx3) or not changed (Gsto1) during recurrent hypoglycemia." (PMID 26918849, 2016).
infertile (2 papers, 2022). "Weight loss of more than 10 kg in infertile patients with PCOS significantly reduces gene expression of GPX3." (PMID 36246893, 2022). "Previous reports asserted that deletion or reduction of Ptx3 and Gpx3 expression levels in mice results in the failure of oocyte fertilization and infertility." (PMID 34991678, 2022).
Myalgia (2 papers, 2022 to 2025). "Furthermore, the combined presence of GSTP1 Ile and GSTO1 Ala alleles exhibited cumulative risk regarding long-COVID myalgia in carriers of the combined GPX1 LeuLeu/GPX3 CC genotype." (PMID 35624818, 2022). "The combined effect of risk genotypes (GSTP1 AB IleIle, GSTO1 AlaAla, GPX1 LeuLeu, and GPX3 CC) markedly increased the probability of myalgia, suggesting a cumulative genetic burden." (PMID 40867811, 2025).
Myocardial fibrosis (2 papers, 2022 to 2025). "The scRNA-seq analysis was used to characterize the dynamic changes associated with fibroblast differentiation and identified Gpx3 as a factor that might be involved in the regulation of myocardial fibrosis under cardiac pressure overload." (PMID 35799890, 2022). "Along with CM survival, GPX3 inhibited adverse ventricular remodelling and myocardial fibrosis, and promote cardiac repair and functional recovery." (PMID 39900557, 2025).
polycystic ovary syndrome (2 papers, 2019 to 2022). A disorder that manifests as multiple cysts on the ovaries. "As such, GPX3 is proposed as a biomarker of embryo quality for polycystic ovary syndrome patients." (PMID 34980157, 2022).
prediabetes (2 papers, 2024). "Lower GPx3 values were observed in the patients with prediabetes and T2DM compared to the control group." (PMID 38791447, 2024). "In prediabetes probands, we observed a trend toward a GPx3 decrease." (PMID 38791447, 2024). "Finally, we have shown downregulation of Glutathione peroxidase 3 (GPX3 gene) in the prediabetes group, which is vital in managing oxidative stress and enhancing antioxidant defense mechanisms." (PMID 39085321, 2024). "Taking into account the natural development of T2DM, which is preceded by many years of prediabetes, it seems that the level of GPx3 may slightly decrease." (PMID 38791447, 2024). "Surprisingly, a positive correlation emerged between GPx3 levels and the TG/HDL ratio in the prediabetes group." (PMID 38791447, 2024). "Our findings included a significant GPx3 reduction in the CMD patients (n = 126), especially in the T2DM patients (n = 51), and a decreasing trend in the prediabetes group (n = 37)." (PMID 38791447, 2024). "Additionally, an inverse relationship was found between FPG and GPx3 in the CMD and prediabetes groups." (PMID 38791447, 2024). "Then, the level of GPx3 in the T2DM and prediabetes groups was analyzed separately." (PMID 38791447, 2024). "The obtained results demonstrate that although decreased GPx3 levels could indicate CMD in T2DM patients, they fail to consistently signal the earlier stages, such as prediabetes." (PMID 38791447, 2024). "In our study, a negative correlation was observed between triceps skinfold thickness and GPx3 levels in the control group, though no such associations were found for other skinfold sites or within the CMD, prediabetes, and T2DM groups." (PMID 38791447, 2024). "Moreover, there was a positive moderate correlation in the prediabetes group between the level of GPx3 and TG/HDL and a negative moderate correlation with HDL concentration." (PMID 38791447, 2024). "Therefore, the lack of a clear decline in the GPx3 levels in people with prediabetes suggests that GPx3 may not be a reliable early indicator of CMDs." (PMID 38791447, 2024). "In the prediabetes and T2DM groups, the only significant finding was a moderate negative correlation between GPx3 levels and SBP, particularly in the T2DM subgroup." (PMID 38791447, 2024). "The analysis of the prediabetes and T2DM groups showed only a negative moderate correlation between the level of GPx3 and SBP in the T2DM group." (PMID 38791447, 2024).
preeclampsia (2 papers, 2024). Preeclampsia is a hypertensive disorder of pregnancy that is characterized by new-onset hypertension with proteinuria presenting after 20 weeks of gestation, and depending on mild or severe forms may initially present with severe headache, visual disturbances, and hyperreflexia. "In the specific context of Preeclampsia, the significance of GPX3, a selenoprotein with antioxidant properties, emerges." (PMID 38628314, 2024). "Furthermore, differential expression of GPX3 in the placenta during normal and preeclamptic pregnancies underscores its potential involvement in the pathophysiology of Preeclampsia." (PMID 38628314, 2024).
renal carcinoma (2 papers, 2015 to 2022). A carcinoma arising from the epithelium of the renal parenchyma or the renal pelvis. "Full or partial methylation was detected in five renal cancer cell lines (786-0, Caki-1, Osrc-2, Kert-3 and 769P), which showed downregulated GPX3 expression, whereas only weak or no methylation was detected in the cell lines (Hek293 and HK-2) with GPX3 expression." (PMID 25970749, 2015).
renal failure (2 papers, 2021 to 2024). "Accordingly, the plasma’s GPx3 activity appears to be related both to selenium status and renal function as it is reduced in renal failure, and the reduction is associated with the severity." (PMID 39765894, 2024). "In the mouse renal insufficiency model, ADMA was elevated to a similar extent in wildtype and GPx3-deficient mice; however, platelets from GPx3-deficient mice were more sensitive to ADMA-induced aggregation than those from wild type mice." (PMID 34579115, 2021). "In acute kidney failure following cardiac surgery, GPx3 is reduced and may serve as a prognostic factor for renal failure." (PMID 39765894, 2024). "Previous studies have observed that GPx3 is reduced in renal failure." (PMID 39765894, 2024). "Hence, reduction in GPx3 is not only related to severely reduced renal function such as patients on haemodialysis or patients with acute renal failure." (PMID 39765894, 2024).
rheumatoid arthritis (2 papers, 2023 to 2025). A chronic, systemic autoimmune disorder characterized by inflammation in the synovial membranes and articular surfaces. "In autoimmune diseases like rheumatoid arthritis (RA), Se’s effect on GPx3 is critical." (PMID 39942544, 2025).
tendinopathy (2 papers, 2023 to 2024). "This steroid-free approach for upregulation or activation of GPX3 can serve as a novel therapeutic strategy for tendinopathy." (PMID 37021050, 2023). "The optimum expression of GPX3 required for preventing tendinopathy needs to be investigated further." (PMID 37021050, 2023). "We found that the expression of GPX3 was significantly lower in tissues from patients with tendinopathy than in normal tissues, and GPX3 had a very high expression among all the antioxidant enzymes examined; both findings supported our notion." (PMID 37021050, 2023). "Overexpression and/or knockdown of GPX3 in tendon tissues by lentivirus or examination of tendons from Gpx3 knockout mice may provide valuable information regarding the effect of GPX3 on tendinopathy." (PMID 37021050, 2023). "Further studies are required to determine the role of GPX3 in tendons and tendinopathy." (PMID 37021050, 2023). "Notably, Gpx3 plays a crucial immunomodulatory role in cancer by regulating various pathways that counteract the effects of ROS In a recent study, it was demonstrated that increased expression of Gpx3 prevents tendinopathy in rats by effectively suppressing oxidative stress." (PMID 38721062, 2024).
thyroid (2 papers, 2020 to 2021). "We hypothesized that natural autoantibodies to SELENOP are prevalent in thyroid patients, impair Se transport, and negatively affect GPX3 biosynthesis." (PMID 34884891, 2021).
type 1 diabetes (2 papers, 2011 to 2023). "Frequency of CYBA - 657 T → A (unregistered), GCLC - 129 C → T (rs17883901) and GPX3 - 65 T → C (rs8177412) polymorphisms in type 1 diabetes patients and non-diabetic control subjects." (PMID 21962117, 2011). "Notably, the GPX3 peptide was also significantly more abundant in the type 1 diabetes group." (PMID 37537394, 2023). "Moreover, the direction of change in GPX3 during the first year was indicative of subsequent fasting C-peptide/glucose levels, and supports further investigation of this and other serum protein measurements in future studies of beta cell function in type 1 diabetes." (PMID 37537394, 2023).
adenoid cystic carcinoma (1 paper, 2023). A malignant tumor arising from the epithelial cells. "However, in PRAD, HNSC, KIRC, BRCA, KIPA, skin cutaneous melanoma (SKCM), bladder urothelial carcinoma (BLCA), and adenoid cystic carcinoma (ACC), GPX3 expression was lower in the higher T stage." (PMID 36845676, 2023).